SYP (synaptophysin)
Diseases named in the same sentence as SYP in open-access papers (continued):
Sharing a sentence is not in itself a finding about the gene and the disease.
adenocarcinoma (continued). "In addition, some of the adenocarcinomas bordering the NEC were positive for synaptophysin." (PMID 36044167, 2022). "In addition, some of the adenocarcinomas bordering the NEC stained positive for synaptophysin." (PMID 36044167, 2022). "Specifically, the pre-castrated LTL-331 PDX initially exhibited a classic adenocarcinoma phenotype and gradually transformed to the t-NEPC LTL-331R PDX after surgical castration, during the process EHF was notably depressed and positively associated with AR, and negatively with SYP and SOX2." (PMID 33414441, 2021). "On histopathology, the scalp tumor demonstrated an immunohistochemical profile supportive of an adenocarcinoma (pankeratin+, CEA+) with neuroendocrine differentiation (synaptophysin+) and hormonal receptor positivity (ER+, PR+, androgen receptor positivity)." (PMID 41143220, 2025). "Positive markers for the adenocarcinoma component included CK8/18, CDX2, and C-erB-2, whereas positive markers for the neuroendocrine component included chromogranin A, synaptophysin, CD56, and a high Ki-67 index (~40%)." (PMID 40909957, 2025). "To further confirm our H&E results, we conducted immunostaining for the adenocarcinoma marker AR and the NEPC markers SYP and CD56." (PMID 33009820, 2021). "On IHC, the adenocarcinoma component stained positively for CDX2 and pancytokeratin, and the neuroendocrine component stained positively for synaptophysin and chromogranin." (PMID 34258127, 2021). "Chromogranin A, synaptophysin, CD56, CK35BH11 were used for the neuroendocrine lineage and AE1/AE2, CDX2, CK7, CK20 to confirm the existence of adenocarcinoma cells." (PMID 34201925, 2021). "In our study, an immunohistochemistry panel with specific markers was performed in all MiNEN cases, evidencing the presence of both neuroendocrine components (chromogranin A, synaptophysin, CD56, CK35BH11) and adenocarcinoma cells (AE1/AE2, CDX2, CK7, CK20)." (PMID 34201925, 2021). "Pathology review and immunohistochemistry for phenotypic markers (AR, PSA, PSMA, ERG, chromogranin A, synaptophysin, and CD56) showed that 9 research-ready PDXs are adenocarcinoma, 7 are neuroendocrine, and 1 has mixed pathology." (PMID 34413304, 2021). "He underwent biopsy of one liver lesion, and pathology demonstrated poorly differentiated adenocarcinoma with focal neuroendocrine differentiation (CK7+, CDX2+, synaptophysin/chromogranin+, CK20−, TTF1−, napsin−) consistent with pancreatic or biliary origin." (PMID 31371345, 2019). "The 1002 conventional adenocarcinomas included 763 synaptophysin-negative (76%) and 239 synaptophysin-positive tumors." (PMID 34680258, 2021). "Patients with “true” MANECs, on the other hand, showed a significantly shorter survival than all conventional adenocarcinomas with or without synaptophysin expression in uni- and multivariate analyses (e.g., multivariate DSS: p < 0.001, HR: 5.20)." (PMID 34680258, 2021). "The most interesting observation was from patient #4, a histologically diagnosed adenocarcinoma, in which we found that when compared with other epithelial clusters, cluster 5 preferentially expressed NE markers CHGA and SYP, probably representing a population of early NE precursors." (PMID 33328604, 2020). "Immunohistochemically, the adenocarcinoma cells were negative for chromogranin A and synaptophysin, whereas the round-shaped carcinoma cells were diffusely positive for synaptophysin but negative for chromogranin A and p40." (PMID 29740725, 2018). "Immunohistochemically, the adenocarcinoma cells were positive for CEA but negative for chromogranin A (CgA) and synaptophysin (Syn), while the non-adenocarcinoma cells were positive for the expression of CgA and Syn but negative for CEA." (PMID 27848241, 2016). "One HAC patient had specific staining for Cromogranin A (CgA) and CD56, which were focally positive in both adenocarcinoma and hepatoid areas, illustrating neuroendocrine carcinomatous features, while synaptophysin (SYN) was negative." (PMID 24669215, 2014).
adenocarcinoma (continued). "The adenocarcinoma component was strongly positive for cytokeratin 7 and pancytokeratin, weakly positive for synaptophysin and CD56, and negative for carbonic anhydrase IX, CD99, CDX2, chromogranin, cytokeratin 20 and smooth muscle actin." (PMID 19523243, 2009). "Histology confirmed completely resected stage IIA (pT3pN0) moderately differentiated adenocarcinoma with a 10% component of neuroendocrine carcinoma, on the basis of positive staining for synaptophysin and chromogranin—not present in the adenocarcinoma components." (PMID 40162154, 2025). "Of note, immunostaining showed that all seven tumors were adenocarcinomas before the treatment, evidenced by staining positive for both AR and PSA, and staining negative for SYP, CD56, and CgA, whereas most of them became AR‐ and PSA‐negative, and SYP‐, CD56‐, and CgA‐positive after ADT." (PMID 33009820, 2021). "The case with the associating adenocarcinoma component showed similar immunohistochemical profile (including EGFR expression) in both tumors, except for the lack of CD56, synaptophysin and chromogranin expressions and the presence of CEA expression in the adenocarcinoma." (PMID 17803816, 2007). "However, the biological behavior of adenocarcinomas that express synaptophysin but do not show a typical neuroendocrine morphology remains unclear." (PMID 34680258, 2021). "Furthermore, our data suggest that conventional adenocarcinomas with a diffuse synaptophysin expression should not be classified as MANECs, also strongly arguing that synaptophysin testing should be reserved for carcinomas with an H&E morphology suggestive of a neuroendocrine differentiation." (PMID 34680258, 2021). "The predominant adenocarcinoma component stains positive for P16 and CAM 5.2, focally positive for CEA, ER, and P40, and negative for vimentin, synaptophysin, and chromogranin." (PMID 41589095, 2026). "Immunohistochemically, the NEC cells were diffusely positive for synaptophysin, with focal expressions of INSM1, chromogranin A and NCAM, whereas the adenocarcinoma cells were mostly negative for these NE markers." (PMID 35801304, 2022). "Cells of the adenocarcinoma component were CAM.5.2, CK7, CK AE1/AE3, and GATA-3 positive and negative for synaptophysin, chromogranin A, parathormone, parafibromin, thyroglobulin, TTF1, calcitonin, glucagon, S100, PGP-9 and Bcl-2." (PMID 32506375, 2021). "Pathology showed adenocarcinoma immunohistochemically consistent with lung primary (TTF-1 positive, Napsin A positive, CK7 positive, CK20 negative, synaptophysin negative, chromogranin negative)." (PMID 32560187, 2020). "Lung biopsy revealed a poorly differentiated adenocarcinoma with immunohistochemistry (IHC) positive for CEA, CK20, CDX2, and negative for CK7, TTF-1, Napsin A, synaptophysin, and chromogranin." (PMID 27171493, 2016). "All adenocarcinoma were positive for either PSA and/or PSMA on IHC while none expressed chromogranin-A, synaptophysin, or CD56 (N-CAM) except one focally positive for synaptophysin." (PMID 29147414, 2015). "It is characterized by small neuroendocrine (NE)-like cells which typically express NE markers such as chromogranin A (CHGA) and synaptophysin (SYP) and do not express androgen receptor (AR) or adenocarcinoma markers, such as prostate-specific antigen (PSA)." (PMID 25544761, 2015). "CDX2, mCEA, CD56, synaptophysin, NSE and chromogranin can help differentiate it from non-endocrine poorly differentiated adenocarcinoma." (PMID 17803816, 2007). "The immunophenotype and morphology of the lung lymph node are similar to the previous cervical biopsies, although the cervical biopsies also revealed an additional well-differentiated adenocarcinoma component that stained positive for p16 and negative for TTF-1, synaptophysin, and CD56." (PMID 41589095, 2026).
adenocarcinoma (continued). "Imaging and pathology revealed distinct morphologic and immunohistochemical profiles: hepatic biopsy confirmed large-cell NEC positive for synaptophysin and CD56, whereas rectal biopsy showed adenocarcinoma with intestinal markers and no neuroendocrine differentiation." (PMID 40671972, 2025). "The histological review identified LU2E as an SCLC sample, showing positive staining for chromogranin A, synaptophysin, and CD56, but negative for NapsinA, whereas LU2D was identified as an acinar predominant adenocarcinoma, with negative staining for chromogranin A and synaptophysin." (PMID 37799479, 2023). "The adenocarcinoma component was strongly and diffusely immunoreactive (3+, cytoplasmic staining) for CK7 and pancytokeratin; weakly and focally immunoreactive (1+, cytoplasmic staining) for CD56 and synaptophysin; and negative for CA-IX, CD99, CDX2, chromogranin, CK20 and SMA." (PMID 19523243, 2009).
cancer (69 papers, 2005 to 2025). A tumor composed of atypical neoplastic, often pleomorphic cells that invade other tissues. "Of the 10 mice with cancer, only three pancreata had SYP+ cells associated with PDAC." (PMID 35574446, 2022). "In addition, we observed that clone P1C3 was SYP high, consistent with the association of neuroendocrine differentiation with an aggressive behavior in certain cancers, i.e., the prostate." (PMID 35565186, 2022). "3D-iNET ORION cancer cell line showed high potential to form tumorspheres when embedded in Matrigel matrix and expresses synaptophysin and EpCAM." (PMID 39103560, 2024). "In fact, some genes related to synaptic physiology e.g. Synaptophysin were detected in cells of this cancer entity." (PMID 39592661, 2024). "Cancer cells that differentiate into endocrine cells are positive for the endocrine markers, chromogranin, and synaptophysin." (PMID 38945017, 2024). "Negativity for Chromogranin A and Synaptophysin excluded carcinoma subtypes with neuroendocrine differentiation as described for both species (Data not shown)." (PMID 39696035, 2024). "ALK immunoreactivity was also significantly associated with expression of cancer stem cell (CSC)-related molecules (cytoplasmic CD133, ALDH1, Sox2) and neuroendocrine markers (CD56 and synaptophysin)." (PMID 37592266, 2023). "The cancer cells express synaptophysin (SYP), chromogranin A (CgA), somatostatin receptor 2 (SSTR2) and gastrin (often focal)." (PMID 36830839, 2023). "Tissue diagnosis require haematoxylin and eosin stains to demonstrate the neuroendocrine phenotype along with immune histochemistry for synaptophysin and chromogranin-A and for carcinoma markers." (PMID 36078951, 2022). "Colorectal MANECs are highly aggressive carcinomas defined by a distinct neuroendocrine morphology and positivity for synaptophysin in the neuroendocrine component." (PMID 34680258, 2021). "These cancers have positive immunohistochemical neuroendocrine markers which include synaptophysin, chromogranin A, CD56, and/or NSE." (PMID 31752927, 2019). "A biopsy of an anterior chest wall nodule demonstrated high-grade poorly differentiated carcinoma with necrosis, which stained strongly positive for thyroid transcription factor-1 and synaptophysin on immunohistochemistry." (PMID 27250121, 2016). "The microscopic examination revealed that the mass was composed of a monotonous population of small cells and that the cells of the carcinoma were positive for cluster of differentiation 56, chromogranin A and synaptophysin." (PMID 24520292, 2014). "Cancer cells stained positive for both synaptophysin and chromogranin A (individual reactivity rate 100%)." (PMID 23734899, 2013). "Immunocytochemistry involves a carcinoma marker containing cytokeratine, and neuroendocrine differentiation is based on markers containing chromogranin, synaptophysin, and neuron-specific enolase." (PMID 23476846, 2013). "Almost all carcinoma cells consisting of invasive and intraductal parts were positive for synaptophysin and neuron-specific enolase." (PMID 23738176, 2013). "Both cancers stain strongly for synaptophysin, calcitonin, and CEA." (PMID 36578797, 2022). "Therefore, our data strongly suggest that synaptophysin testing should be restricted to carcinomas whose morphology on H&E-stained sections indicates a neuroendocrine differentiation." (PMID 34680258, 2021). "All carcinomas were positive for chromogran A, while only two cases were reactive to synaptophysin." (PMID 33469557, 2020). "Additionally, cultivated cells were positive for the neuroendocrine marker synaptophysin underscoring the establishment of the relevant cancer stem cells." (PMID 31804333, 2019). "The use of chromogranin and synaptophysin immunohistochemistry in a case of even lower suspicion of NEBC could help to find these cancers more precisely." (PMID 28118820, 2017).
cancer (continued). "While synaptophysin and chromogranin proteins may be secreted by both normal and cancer endocrine cells, their expression is usually higher in malignant cells." (PMID 28523075, 2017). "Immunohistochemistry (IHC) was nonspecific and inconsistent (positive for pancytokeratin, PAX8, and CDX2, and negative for CK7, CK20, ER, WT1, calretinin, CD31, CD34, and synaptophysin) and working diagnosis was a putative upper gastrointestinal versus mullerian cancer profile." (PMID 27171493, 2016). "In this context, it is of note that two of the four carcinomas with neuroendocrine differentiation in the present study only expressed chromogranin A or synaptophysin and not both of these markers, arguing for a routine immunohistochemical panel including both chromogranin A and synaptophysin." (PMID 24701575, 2014). "Importantly, routinely used diagnostic markers such as chromogranin A or synaptophysin were not among the highly enriched markers in our proteomics analysis and may thus fail to identify the neuroendocrine differentiation of these cancers." (PMID 36443295, 2022). "Chromogranin A, synaptophysin, S-100B protein and GFAP are well known neuroendocrine markers involved in cancer and in neurological diseases." (PMID 31263455, 2019). "FGFR1 expression was associated with higher pN (p = 0.023), pT (p = 0.003) stages, lymphovascular invasion (p = 0.010), p-cadherin (p = 0.028), synaptophysin (p = 0.009) and SOX2 expression (p = 0.034) in luminal A cancers." (PMID 26673008, 2016). "Among the NE markers, synaptophysin was variably positive in two NUT carcinomas (2/6, 33%); however, all cases were negative for ASCL1, chromogranin A, and CD56." (PMID 38326851, 2024). "ASCL1 KO tumors developed a poorly differentiated carcinoma without detectable expression of the NE lineage markers SYP, INSM1, or DLL3 but showed higher expression of NOTCH2, HES1, and KRT8." (PMID 39024561, 2024). "Firstly, we compared the expression of CgA and SYP between malignant tumors and corresponding non-cancerous tissues." (PMID 36899368, 2023). "In addition, some cancer cells were positive for CD56, chromogranin A, and synaptophysin, indicating focal NED." (PMID 31281709, 2019). "Immunohistochemically, these carcinoma cells were negative for all three neuroendocrine markers, i.e., synaptophysin, chromogranin A and CD56, TTF-1, CEA, CK20, h-caldesmon, α-SMA, calponin, and CD10, but specifically positive for 34βE12, CK7 and p63." (PMID 23231806, 2012). "Notably, no K18−K5+SYP+ cells were found in any of the 297 cancer tissues." (PMID 33328604, 2020). "DEK::AFF2 carcinomas consistently express squamous cell markers, such as p40, CK5/6 and p63, while typically negative for synaptophysin, NUT, and p16." (PMID 40299135, 2025). "Biopsy and immunohistochemical findings including negative Synaptophysin and Chromogranin A staining and positive Trypsin and BCL10 staining suggested a carcinoma with acinar cell differentiation." (PMID 38625458, 2024). "Generally, this NE phenotype is positive for markers of other high-grade NE carcinomas, such as chromogranin A(CHGA), neuron-specific enolase (NSE), synaptophysin (SYP), and CD56, and negative for luminal prostate differentiation markers." (PMID 37455903, 2023). "While the presence of chromogranin A and synaptophysin expression suggests NED, it does not necessarily mean NEPC; immunohistochemical analysis of metastatic hormone-sensitive prostate cancer reveals that 61% of primary cancer specimens are positive for chromogranin A." (PMID 38962044, 2024).
cancer (continued). "Undifferentiated carcinoma was confirmed based on the presence of small round atypical cells with the formation of a solid alveolar lesion on histopathological examination and immunohistochemical staining that was positive for CAM 5.2 but negative for chromogranin A and synaptophysin." (PMID 28063144, 2017).
neurodegenerative disease (18 papers, 2012 to 2025). A disorder of the central nervous system characterized by gradual and progressive loss of neural tissue and neurologic function. "Progressive loss of synaptophysin density has been reported in transgenic HD and other neurodegenerative disease mouse models." (PMID 28176805, 2017). "synaptophysin persisted well after cessation, suggesting these alterations to the CNS are not transient and may be responsible for the long-term risk of neurodegenerative diseases." (PMID 35351173, 2022). "Growth-associated protein 43 (GAP43) and synaptophysin (Syn) are synaptic proteins that are associated with axonal sprouting and synaptogenesis in various neurodegenerative diseases and may accumulate in regenerating neurons and axons." (PMID 28302146, 2017). "Since neuroinflammation is associated with synaptic markers loss, which may result in cognitive dysfunction and neurodegenerative diseases, we measured the expression of synaptic proteins, synaptophysin (pre-synaptic), and PSD95 (post-synaptic) in primary neurons." (PMID 37693917, 2023). "Neurodegenerative diseases like AD are associated with increased neuroinflammatory markers (e.g., IL-1β and TNF-α) and loss of synaptic markers (e.g., synaptophysin and drebrin)." (PMID 35742911, 2022). "The synaptic proteins such as post-synaptic density protein 95 (PSD-95), synaptophysin (SYN), and synaptosomal associated protein 23 (SNAP23) are essential for regulating various neurotransmitters and have been found to be modified in neurodegenerative diseases." (PMID 39355174, 2024). "Unlike synaptophysin, CSPalpha has been implicated in the export of neurodegenerative disease-associated misfolded proteins, including tau, TDP-43, and alpha-synuclein in vitro." (PMID 35928052, 2022).